HNF4A (hepatocyte nuclear factor 4 alpha)
Diseases named in the same sentence as HNF4A in open-access papers (continued):
Sharing a sentence is not in itself a finding about the gene and the disease.
hepatocellular carcinoma (continued). "The results showed that knocking down either HNF4α or Exo70 in human hepatoma cells reduced the expression of Cdc2, while had no influence on the expression of Cyclin B1 and Cdk7." (PMID 26848864, 2016). "We also describe the transcriptional partners of TCF7L2 and, in particular, identify the master-regulator hepatocyte nuclear factor 4-alpha (HNF4α), as a key transcriptional partner of TCF7L2 in the hepatoma cells, particularly in the regulation of metabolic genes." (PMID 25414334, 2014). "Compared to COS-7 and HeLa cells, mouse Hepa 1.6 and rat H4IIEC3 hepatoma cells express large amount of endogenous WT HNF4α (data not shown)." (PMID 21437216, 2010). "Additionally, we analyzed the clinical correlations of KDM1A expression level, ZMYM3 expression level, liver-TE-related gene expression profiles, and HNF4A downstream gene expression profiles in the TCGA and ICGC hepatocellular carcinoma expression profile datasets." (PMID 38965210, 2024). "In hepatocellular carcinoma, an PRMT7 enhancer was found to bind to the transcription factor HNF4A to promote the expression of the host gene PRMT7, which ultimately contributes to HCC pathogenesis." (PMID 38849954, 2024). "There has been no previous report on HBx-mediated downregulation of HNF4α in human hepatoma cells." (PMID 32023898, 2020). "Downregulation of HNF4α is described in renal cell carcinoma (RCC), hepatocellular carcinoma (HCC) and cirrhotic tissue, colorectal carcinoma, and rodent models of HCC." (PMID 31695151, 2020). "Transfections of HNF4A, HNF1A and FoxA3 suppressed hepatocellular carcinoma (HCC) cell proliferation, suggesting tumor suppressive roles of FoxA3 in HCC." (PMID 32151057, 2020). "Overexpression of Exo70 in human hepatoma PLC/PRF/5 cells corrected the dysregulated cell cycle caused by knocking down endogenous HNF4α; in contrast, overexpressing HNF4α showed no influence on the G2/M cell cycle arrest induced by knocking down endogenous Exo70." (PMID 26848864, 2016). "Moreover, we also recently have reported that the combination of HNF1A, HNF4A, and FOXA3 synergistically reprograms the hepatocellular carcinoma (HCC) cells to hepatocyte-like cells." (PMID 34141708, 2021). "Finally to test whether HNF4α was required for the full effect of Tcf7l2 silencing on gene expression in the hepatoma cells, we analyzed the effect of Hnf4a silencing with and without concomitant Tcf7l2 silencing on a subset of our DEGs." (PMID 25414334, 2014). "Interestingly, enforcing expression of HNF4α, in cooperation with Forkhead Box Protein A3 (FOXA3) and Hepatocyte Nuclear Factor 1-Alpha (HNF1α), could even reverse the hepatocellular carcinoma (HCC) cells into normal hepatocyte-like cells." (PMID 36249028, 2022).
type 2 diabetes (129 papers, 2008 to 2026). "Hepatocyte nuclear factor 4 alpha (HNF4α) mutations are associated with maturity-onset diabetes of the young." (PMID 41438090, 2025). "Consistently, reduced Lp(a), apolipoprotein (AII), and apolipoprotein (CIII) levels have been observed in patients with maturity-onset diabetes of the young (MODY) carrying the HNF4A (Q268X) mutation." (PMID 40370778, 2025). "Elevated ACE expression was linked to maturity onset diabetes of the young, and HNF4A was enriched in pyruvate metabolism." (PMID 40995593, 2025). "Rare variants in GCK, HNF1A and HNF4A are recognised as causes of maturity onset diabetes of the young." (PMID 39097650, 2024). "While GCK, HNF4A were already well-recognised as causes of maturity onset diabetes of the young (MODY), the implication of GIGYF1 was novel though was quickly confirmed in another study which had access to sequence data from 379,000 UK Biobank participants." (PMID 39666780, 2024). "This approach also shed light on a potentially activating effect of a HNF4A type 2 diabetes risk variant." (PMID 38909044, 2024). "Mutations in HNF4A are associated with a monogenic form of type 2 diabetes and the loss of function in mice, causing severe hepatomegaly and steatosis and resulting in premature death." (PMID 36835193, 2023). "HNF4A crucially performs hepatic gluconeogenesis regulation and insulin secretion, and the corresponding gene was shown to be linked to type 2 diabetes (T2DM) in several studies." (PMID 36360783, 2022). "Numerous large-scale genetic investigations have established those common variations of the HNF1A and HNF4A genes are also associated with type 2 diabetes, implying that they play a role in the etiology of both disorders." (PMID 36037214, 2022). "Rare loss-of-function variants of HNF1A and HNF4A can cause the mendelian disorder mature-onset diabetes of the young." (PMID 35387486, 2022). "The HNF4α activators were alverine and benfluorex, known drugs that have been used for irritable bowel syndrome and weight loss/type 2 diabetes, respectively." (PMID 34117215, 2021). "Previous studies have found that HNF4α is a key regulator of a number of genes involved in glucose, cholesterol and fatty acid metabolism, and HNF4α mutations cause monogenic type 2 diabetes of the young." (PMID 30405404, 2018). "Inactivating mutations in HNF1A and HNF4A causes congenital HH in children and then maturity-onset diabetes of youth (MODY type 3 in HNF1A and type 1 in HNF4A)." (PMID 28855921, 2017). "Loss-of-function mutations in HNF4A gene have been shown to cause a monogenic form of type 2 diabetes as well as type 1 maturity-onset diabetes of the young (MODY1)." (PMID 29216278, 2017). "The p.T130I HNF4A mutation is associated not only with MODY but also with the development of the common late-onset form of type 2 diabetes." (PMID 26981542, 2016). "Eight additional HNF4α mutations have been associated with type 2 diabetes: F75fsdelT, K99fsdelAA, R154X, G115S, R127W, V255M, E276Q, and V393I." (PMID 26110391, 2015). "This study reports the first patient with an HNF4A mutation to have been serially monitored from the diagnosis of hyperinsulinaemic hypoglycaemia to maturity-onset diabetes of the young." (PMID 24299156, 2014). "Maturity-onset diabetes of the young can develop as early as the first decade of life in persons with an HNF4A mutation." (PMID 24299156, 2014). "HNF4A mutations cause hyperinsulinaemic hypoglycaemia in early life and maturity-onset diabetes of the young." (PMID 24299156, 2014). "The remaining SNPs were directionally consistent with South Asian estimates and three (AP3S2 rs2028299, GRB14 rs3923113 and HNF4α rs4812829) were nominally (p < 0.05) associated with type 2 diabetes in DIAGRAM." (PMID 25145545, 2014).
type 2 diabetes (continued). "A meta-analysis of polymorphisms in the promoter and along the entire coding region of the HNF4A gene and type 2 diabetes in 49.577 individuals revealed significant associations for more than one locus." (PMID 22523693, 2012). "The genes regulated by hepatic nuclear factors, Hnf1A (n = 112 target molecules in the dataset) and Hnf4A (n = 527) TRs, whose mutations are known to cause maturity-onset diabetes of the young (MODY) and insulin-independent diabetes mellitus, were predicted to be inhibited by CUR." (PMID 35017319, 2022). "HNF1A and HNF4A are established genes causing maturity-onset diabetes of the young (MODY)." (PMID 34362956, 2021). "Firstly, as HNF4G is not expressed in pancreatic tissue according to The Human Protein Altas, we selected HNF4A (hepatocyte nuclear factor 4) because of its crucial role in pancreatic β-cells development and since its mutations cause a type of maturity-onset diabetes of the young." (PMID 31443431, 2019). "Furthermore, HNF4A mutation has been reported to be associated with impaired insulin secretion, resulting in maturity-onset diabetes of the young, and the expression of genes involved in liver and beta-cell functions, such as, glucose transport and glycolysis." (PMID 29598821, 2018). "In addition to IBD, human HNF4A variants are associated with metabolic syndrome and type 2 diabetes." (PMID 28385711, 2017). "HNF4A, a nuclear receptor transcription factor, has been linked to developmental and metabolic functions, and to several diseases, including maturity-onset diabetes of the young and type 2 diabetes." (PMID 23071669, 2012). "Gene variants of HNF4α are also associated with type 2 diabetes." (PMID 22190905, 2011). "As loss of HNF4A is linked to type II diabetes and plays a crucial role in MODY1, it is most relevant to learn whether miR-34a and miR-21 are dysregulated in pancreatic β-cells of patients." (PMID 22140441, 2011). "Moreover, this network was centered primarily on the hepatic nuclear factor 4α (HNF4A), a transcription factor that has been strongly implicated in an early-onset form of type II diabetes, maturity onset diabetes of the young." (PMID 20126273, 2010). "Variation in the P2 promoter of HNF4A, presumably leading to a decrease in HNF4A expression, has been associated with an increased risk of developing Type 2 diabetes, whilst bi-allelic inactivation of HNF1A and HNF1B has been shown to cause a number of types of cancer." (PMID 19787084, 2008). "With the hepatocyte nuclear factor 4α (HNF4α) gene, the pancreas-specific transcription start site is located 45 kb upstream relative to that of the liver form, and SNPs within the distal promoter region showed significant association with Type 2 diabetes." (PMID 18199129, 2008). "Similarly, variants of the KCNJ11 and HNF4A genes could cause MODY or type 2 diabetes, depending on how the variant affects the protein function." (PMID 38932873, 2024). "HNF4α has been demonstrated to activate insulin gene expression indirectly via inducing the level of hepatic nuclear factor 1 and also directly through binding to a cis element of insulin promoter, and is recognized as a cause of maturity onset diabetes of the young, subtype 1." (PMID 25264921, 2014). "The transcription factors HNF4A (MODY1) and HNF1A (MODY3) are best known as causes of maturity-onset diabetes of the young." (PMID 41614934, 2026). "Pathogenic variants in these genes are associated with HNF1A-MODY and HNF4A-MODY, subtypes of maturity-onset diabetes of the young, as well as renal cysts and diabetes syndrome (RCAD), respectively." (PMID 39859454, 2025). "Of note, mutations in subtype-defining transcription factors, including HNF1A, TCF4, NEUROD1 and HNF4A, cause MODY, and their cis-regulatory sites map to type 2 diabetes risk loci." (PMID 40768044, 2025).
type 2 diabetes (continued). "Crystal structure and transcriptional activation studies identify how HNF4A P2 promoter sequence variants bind HNF-1A and highlight disease mechanisms of P2-driven HNF1A-&ndash;maturity-onset diabetes of the young." (PMID 38855865, 2024). "Moreover, common variants in HNF4A have been associated with a moderate increased risk for the development of type 2 diabetes (T2D)." (PMID 38433330, 2024). "A previous study carrying out gene-based weighed burden analysis of rare coding variants using 200,000 exome-sequenced UK Biobank participants identified three genes associated with type 2 diabetes (T2D) at exome-wide significance, GCK, HNF4A and GIGYF1." (PMID 39666780, 2024). "While FOXA2 has been shown to control mRNA levels of PDX1, HNF1A, and HNF4A, mutations in HNF1A, HNF1B, HNF4A, and PDX1 are known to cause maturity-onset diabetes of the young (MODY)." (PMID 39322760, 2024). "BBR suppresses the HNF-4α miR122 pathway in type 2 diabetic mice, which attenuates gluconeogenesis and lipid metabolism disorder." (PMID 36676074, 2023). "Here the authors show that the fetal isoform of HNF4a is induced in mouse livers upon fasting and in type-2 diabetes in a manner regulated by TET3." (PMID 31953394, 2020). "In the present study, we examined expression of miR122, HNF-4α, and key gluconoegenesis and lipid metabolism enzymes in the liver of type 2 diabetic mice and in palmitate-incubated HepG2 cells after BBR treatment." (PMID 27011261, 2016). "In this study, we screened 6 MODY genes (HNF4A, GCK, HNF1A, IPF1, HNF1B, and NEUROD1) for mutations in a Han Chinese family with suspected early-onset maternally inherited type 2 diabetes." (PMID 26981542, 2016). "Our findings suggest a possibility of impaired incretin response and this is an exciting area to be explored in HNF4A maturity-onset diabetes of the young." (PMID 24299156, 2014). "We describe, for the first time, incretin response in a patient with HNF4A maturity-onset diabetes of the young, which has the potential to influence the management of these patients." (PMID 24299156, 2014). "In conclusion, we report the first patient with HNF4A hyperinsulinaemic hypoglycaemia to have switched to maturity-onset diabetes of the young on serial oral glucose tolerance testing." (PMID 24299156, 2014). "In the present study we elucidate the regulatory potential of the 3′UTR of the HNF4A mRNA to expose the possible regulation of HNF4A in RCC, MODY1 and diabetes type II." (PMID 22140441, 2011). "Heterozygous mutations in the human HNF4α gene lead to maturity-onset diabetes of the young subtype 1 (MODY1) and there is evidence that HNF4α is also a susceptibility gene for common type 2 diabetes." (PMID 19835622, 2009). "Interestingly, chronic glucose/palmitate exposure deregulates HNF1B and HNF4A in human islets, linking glucolipotoxic stress to beta cell subtype dysfunction in type 2 diabetes." (PMID 40768044, 2025). "While the association of rare functionally damaging HNF1A variants with HNF1A-MODY and type 2 diabetes is well established owing to robust functional assays, the impact of HNF4A variants on HNF-4A transactivation in tissues including the liver and kidney is less known, due to lack of similar assays." (PMID 38433330, 2024). "Mutations in the HNF4A and HNF1A genes are the cause of the most frequent type of types 1 and 3 maturity-onset diabetes of the young (HNF1A-MODY), respectively and also represent a risk for type 2 diabetes, metabolic syndrome, coronary heart disease, pancreas and liver cancer and ulcerative colitis." (PMID 35741825, 2022). "miR-122-5p is involved in the inhibition of cardiac fibroblast differentiation induced by apigenin through targeting the transcription factor HIF-1α; it is regulated by another transcription factor HNF4α in type 2 diabetic mice, indicating a regulation between miRNA and TF in different diseases." (PMID 36203804, 2022).
type 2 diabetes (continued). "Our results show that mutations in HNF4A and HNF1A genes might account for this early-onset inherited type 2 diabetes." (PMID 26981542, 2016). "is HNF4A (aka MODY1), which has long been associated with Type 2 diabetes." (PMID 25643280, 2015). "For example, several GWAS loci for type 2 diabetes contain genes known to harbour causal coding variants for rare Mendelian syndromes related to type 2 diabetes (e.g. HNF1A, HNF1B, WFS1, PPARG, KCNJ11, HNF4A, GCK)." (PMID 26702037, 2015). "Impaired incretin response might be contributory in the early stages of HNF4A maturity-onset diabetes of the young." (PMID 24299156, 2014). "Similarly, in human T2D islets, reduced ARNT expression is associated with a reduction in expression of glucose metabolic genes including IRS2, IR, AKT2, G6PI, PFK, PGM and the maturity onset diabetes of the young (MODY) gene HNF-4α." (PMID 24204824, 2013). "However, only the maturity-onset diabetes of the young (MODY) gene HNF4A and the T2D gene CDKN2A in SAT had significant permutation adjusted P-values." (PMID 23251491, 2012). "HNF4α might be a dual PPARα/γ activator, and overexpression of HNF4α may be effective in treatment of type 2 diabetes and dyslipidemia and in preventing atherosclerotic cardiovascular disease." (PMID 22190905, 2011). "From the point of view of genotype–phenotype association, this is not conventional in T1D, since data suggest that HNF4A genetic variants are not necessarily associated with maturity-onset diabetes of the young (MODY) either, because the onset of the disease for all cases was before the age of 9." (PMID 41376825, 2025). "Interestingly, the transcriptional regulator of pancreatic beta-cell function and maturity-onset diabetes of the young (MODY4) gene HNF4A was found to the most significant upstream regulator in the IPA analysis for both PPP (p-value = 0.003; z-score = 0.45) and OD (p-value = 0.0001; z-score = 0.98)." (PMID 30956117, 2019). "Additionally, although no nonsynonymous SNPs or gene expression difference were observed, human GWAS has indicated strong associations of a missense mutation and an intron variant in HNF4a with plasma HDL levels (-log10P = 15.0) and type 2 diabetes (-log10P = 9.5), respectively." (PMID 24586312, 2014). "We reported a chronic increase in TET3 expression in the livers of humans and mice with type 2 diabetes and that TET3 induced Hnf4a promoter demethylation leading to heightened hepatic glucose production and hence hyperglycaemia." (PMID 38216792, 2024). "Hypoglycaemia, hyperinsulinaemic (C1864903) and Diabetes, type 2 (C0011860) were connected through the genes HNF1A, ABCC8, HNF4A, and GCK, as well as the KEGG pathway Type II Diabetes Mellitus." (PMID 30255817, 2018). "The GMDR has been successful in identifying the significant interaction of CHRNA4 with CHRNB2, NTRK2 with BDNF, and GABBR1 with GABBR2 in nicotine dependence, of LEPR and ADRB2 in obesity, and of HNF4A and KCNJ11 in type 2 diabetes (T2D)." (PMID 23626757, 2013). "Metformin, a drug widely used to treat type 2 diabetes, reduces peroxisome proliferator-activated receptor γ coactivator 1α expression and gluconeogenesis in the liver suggesting pharmacological intervention may be successful in decreasing HNF4α-dependent HBV transcription and replication." (PMID 19424486, 2009). "Of the 132 type 2 diabetes Knowledge Portal effector genes, we identified 18 (14%) as candidate effector genes for at least one phenotype, including ABCC8, KCNJ11, NKX2–2, G6PC2, PAM, HNF4A, SLC30A8, RFX6, PCSK1, and GLIS3." (PMID 37333221, 2023). "The utility of routine biochemical biomarkers such as hsCRP or antibodies have been investigated for distinguishing several genetic etiologies (HNF1A, HNF4A, HNF1B) from Type 1 or Type 2 diabetes, or for distinguishing HNF1A specifically from Type 2 diabetes using HDL-cholesterol or hsCRP64–69." (PMID 37794142, 2023).
type 2 diabetes (continued). "We found that our false positive associations with genes WFS1, HNF4A, NPHP4, and TXNL4B were reported to be associated with Type II Diabetes in GWAS Catalog while the others were not." (PMID 33206638, 2020). "In addition, BBR inhibited the expression of nuclear factor HNF-4α, PEPCK and G6Pase in type 2 diabetic rats." (PMID 27011261, 2016). "In particular, both the F-PC2 and E-PC2 networks contain the HNF4A or MODY1 gene, which has long been associated with Type 2 diabetes but not previously associated with asthma." (PMID 25643280, 2015). "Sites annotated to 10 candidate genes for type 2 diabetes, including DUSP9, BCL11A, HNF4A, and CDKN2B, and 7 candidate genes for related metabolic traits (for example, ATP11A, ADCY5 and IRS1) had differential DNA methylation in human pancreatic islets based on sex." (PMID 25517766, 2014). "Validated methylation changes were identified in the promoters of known type 2 diabetes-related genes, including PPARGC1A in muscle (13.9±6.2% vs. 9.0±4.5%, P = 0.03) and HNF4A in adipose tissue (75.2±3.8% vs. 70.5±3.7%, P<0.001) which had increased methylation in type 2 diabetic individuals." (PMID 23251491, 2012).